POLE (DNA polymerase epsilon, catalytic subunit)
Diseases named in the same sentence as POLE in open-access papers (continued):
Sharing a sentence is not in itself a finding about the gene and the disease.
sarcoma (2 papers, 2023 to 2025). A usually aggressive malignant neoplasm of the soft tissue or bone. "To more broadly understand how POLE regulates cellular senescence in CIC::DUX4 sarcoma cells, we conducted transcriptional profiling (RNA-Seq) in POLE-deficient and POLE-replete NCC_CDS1_X1_C1 cells." (PMID 40760094, 2025). "Since POLE expression associates with CIC-fusion expression and has an established role in DNA proofreading and replication, we aimed to investigate the role of POLE in the context of CIC::DUX4 sarcoma." (PMID 40760094, 2025). "To examine the potential role of POLE in inducing apoptosis in CIC::DUX4 sarcoma cells, we silenced POLE or CIC::DUX4 and measured Caspase 3/7 activity." (PMID 40760094, 2025). "Notably, using RNA-seq, we observed that POLE was significantly downregulated following CIC::DUX4 suppression in CIC::DUX4 fusion sarcoma cells, and gene ontology analysis further indicated that POLE was associated with DNA damage and repair pathways." (PMID 40760094, 2025). "Through mechanistic studies we demonstrate that POLE facilitates DNA-repair in CIC::DUX4 sarcomas." (PMID 40760094, 2025). "Using genetic silencing of POLE in CIC::DUX4 sarcoma cell lines, we observed that POLE suppression significantly reduced the growth and/or viability of both NCC_CDS1_X1_C1 and NCC_CDS2_C1 cells, as assessed by Cell-Titer-Glo, trypan blue staining, and crystal violet assays." (PMID 40760094, 2025). "Next, we aimed to determine whether POLE was essential for the survival of CIC::DUX4 sarcoma cells." (PMID 40760094, 2025). "Silencing POLE increased γH2AX and CHK1 phosphorylation relative to control, thus, POLE safeguards against DNA-damage in CIC::DUX4 sarcoma cells." (PMID 40760094, 2025). "Here we show that the catalytic subunit of DNA polymerase epsilon (POLE) is essential for DNA integrity and cellular division in CIC::DUX4 sarcoma." (PMID 40760094, 2025). "To investigate the functional role of POLE in CIC::DUX4 sarcoma, we first examined the effect of POLE suppression on cell-cycle progression in patient-derived CIC::DUX4 sarcoma cells." (PMID 40760094, 2025). "Our data suggested that POLE suppression does not induce cellular death through conventional apoptotic pathways in CIC::DUX4 sarcoma cells, prompting us to investigate alternative mechanisms that limited cellular division and growth." (PMID 40760094, 2025). "For these reasons, we nominated POLE as a key CIC::DUX4 target gene that could potentially regulate DNA repair and replication in CIC::DUX4 sarcomas." (PMID 40760094, 2025). "To further evaluate the therapeutic specificity of targeting POLE in CIC::DUX4 sarcoma cells, we treated NCC_CDS1_X1_C1 and NCC_CDS2_C1 with Aphidicolin, a DNA polymerase inhibitor (no POLE specific inhibitors are commercially available to our knowledge)." (PMID 40760094, 2025). "Interestingly, when CIC::DUX4 was expressed in non-sarcoma cell lines (HEK293T, C2C12, and NIH-3T3), POLE expression remained unaffected, suggesting a cell-context specific response." (PMID 40760094, 2025). "Given these observed cell cycle effects upon POLE suppression, we hypothesized that POLE can, in part, maintain genome stability in CIC::DUX4 sarcoma cells." (PMID 40760094, 2025).
tubular adenoma (2 papers, 2016 to 2019). A usually polypoid neoplasm arising from the glandular epithelium. "Segregation analyses could only be achieved in two of her daughters, detecting POLE:c.141delG; p.Phe48Leufs*6 in one of them, who had been diagnosed of a low grade dysplastic tubular adenoma at the age of 46." (PMID 31285513, 2019).
uterine carcinosarcoma (2 papers, 2021 to 2022). A usually aggressive malignant neoplasm arising from the uterine corpus and less often the cervix. "Potential of an immune checkpoint inhibitor as a promising targeted agent was also shown in a uterine carcinosarcoma patient harboring POLE mutation, reported to occur in about 2–4% of uterine carcinosarcomas." (PMID 34036097, 2021).
uterine corpus cancer (2 papers, 2019 to 2020). A malignant neoplasm involving the body of uterus. "Mutations in the exonuclease domain of POLE are responsible for causing the ultramutator phenotype in colorectal and uterine corpus cancers." (PMID 32838755, 2020).
vulvar carcinoma (2 papers, 2015 to 2025). "Similarly, the DNA repair gene POLE was found mutated in both SCC vulvar cancer groups." (PMID 39789097, 2025). "Similarly, the DNA repair gene POLE was found mutated in both vulvar cancer groups." (PMID 39789097, 2025).
anaplastic thyroid cancer (1 paper, 2018).
cervical tumors (1 paper, 2022). "In contrast to both, cervical tumors were dominated by APOBEC with a small subsets showing the POLE, HRd, and MMRd signatures." (PMID 35109853, 2022).
Cirrhosis (1 paper, 2019). A chronic disorder of the liver in which liver tissue becomes scarred and is partially replaced by regenerative nodules and fibrotic tissue resulting in loss of liver function. "A Caucasian male, 64 years’ old with cirrhosis, TMB 4 mutations/Mb and MSI-low had a pathogenic POLE R762W mutation." (PMID 31258846, 2019).
clear cell renal cell carcinoma (1 paper, 2021). "This study aimed to analyze POLE expression in tumor samples and its prognostic value for patients with clear cell renal cell carcinoma (ccRCC)." (PMID 34950188, 2021).
DNA repair deficiency (1 paper, 2025). "Mutations in the proofreading domain of polymerase epsilon (POLE) result in DNA repair deficiency characterized by MSS and an ultramutated phenotype." (PMID 40236650, 2025).
endometriosis (1 paper, 2021). The growth of functional endometrial tissue in anatomic sites outside the uterine body.
hearing loss (1 paper, 2024). "The genes identified in this study, TNC25 and POLE, have been implicated previously in hearing loss." (PMID 38970134, 2024).
hereditary cancer syndrome (1 paper, 2023). "Germline variations in the DNA polymerase genes, POLE and POLD1, can lead to a hereditary cancer syndrome that is characterized by frequent gastrointestinal polyposis and multiple primary malignant tumors." (PMID 37746257, 2023).
hyperplasia (1 paper, 2022). An abnormal increase in the number of cells in an organ or a tissue with consequent enlargement. "However, two POLE Leu424Val heterozygotes underwent hysterectomy for benign pathology, specifically endometrial dysplasia or hyperplasia, or endometriotic cysts." (PMID 33948826, 2022).
malignant peripheral nerve sheath tumor (1 paper, 2024). Malignant peripheral nerve sheath tumor (MPNST) is a rare and often aggressive soft tissue sarcoma occurring in a wide range of anatomical sites. "Of all 15 patients, ten had POLE mutation (one A252V variant was germline), four had POLD1 mutation (one R682Q variant was germline), and one had malignant peripheral nerve sheath tumor with both POLE and POLD1 mutations." (PMID 39218995, 2024).
medullary carcinoma (1 paper, 2025). "Although POLE-mutant CRCs are generally considered a subtype with a favorable prognosis, they can exhibit high-grade histologic features, including poorly cohesive rhabdoid cells and areas resembling medullary carcinoma." (PMID 40565166, 2025).
metastatic cancer (1 paper, 2023). A carcinoma which has spread from the original site of growth to another anatomic site. "•EGFR, POLE, and PB1 genes had high mutated frequency in the patients with relapse and metastatic cancer." (PMID 37515929, 2023).
metastatic melanoma (1 paper, 2014). A melanoma that has spread from its primary site to another anatomic site. "The DDR1R570Q missense mutation, which we identified in a case of serous EC that was microsatellite-stable and POLE-wildtype, has been identified by others in an endometrioid EC, and in a case of metastatic melanoma." (PMID 25427824, 2014).
metastatic prostate carcinoma (1 paper, 2024). A carcinoma that arises from the prostate gland and has spread to other anatomic sites.
neuroendocrine tumor (1 paper, 2015). "Apart from one neuroendocrine tumor, all POLE mutations occurred in endometrioid ECs." (PMID 25505230, 2015).
pulmonary diseases (1 paper, 2025). "Some other proteins such as TNF and POLE connected with different drugs that are used as anticancer agents and used to treat pulmonary diseases and hematologic malignancy." (PMID 40997149, 2025).
rectal cancer (1 paper, 2025). A primary or metastatic malignant neoplasm that affects the rectum. "0.6% and 0.4% of samples were POLE‐altered in colon and rectal cancer, respectively." (PMID 39865537, 2025).
small intestinal adenoma (1 paper, 2022). "The main symptoms were small intestinal adenoma and adenocarcinoma, and the median survival was lower in POLE-mutant mice than in POLE wild-type mice." (PMID 35780178, 2022).
testis cancer (1 paper, 2024). "Almost all of the top-performing genes were that of over-expression, with PMS2 in THYM; CARD11, LASP1, STIL, POLE, KMT2C, and CLIP1 in testis cancer; ERC1, WRN, OLIG2, FANCC, and ACSL6 in ACC; and SOX2 and NDRG1 in ESCA leading in performance with AUCs ranging 0.832-0.911." (PMID 38491101, 2024).
thymoma (1 paper, 2024). A neoplasm arising from the epithelial cells of the thymus. "Another interesting finding is the observation of POLE mutations in two of the five investigated cases of an exceedingly rare thymoma subtype, namely metaplastic thymoma (MT), which histologically sometimes resembles Type A thymoma." (PMID 38338833, 2024).
tuberous sclerosis (1 paper, 2021). Hereditary disease characterized by seizures, intellectual disability, developmental delay, and skin and ocular lesions. "Among these, the most frequently mutated genes were TSC2 (22 cases), linked to tuberous sclerosis; APC (16 cases), linked to hereditary colon cancer; and the DNA polymerase POLE (16 cases), involved in predisposition to multiple cancers." (PMID 33809641, 2021).
undifferentiated carcinoma (1 paper, 2019). A usually aggressive malignant epithelial neoplasm composed of atypical cells which do not display evidence of glandular, squamous, or transitional cell differentiation. "Although undifferentiated carcinoma was included in the study population in this report, only one out of 34 cases had a POLE mutation." (PMID 31370215, 2019).
urothelial carcinoma of the bladder (1 paper, 2025). "A patient with recurrent urothelial carcinoma of the bladder with POLE p.E277Q mutation achieved a complete response with an anti–PD-1 antibody and had no disease progression for over 3 years." (PMID 40570257, 2025).
tumor (449 papers, 2012 to 2026). "This study describes an unusual case of late metastatic recurrence in a POLE-mutated tumor and provides a review of similar cases in the literature." (PMID 42041738, 2026). "Molecular profiling revealed 90% PD-L1 expression, multiple oncogenic mutations including SMARCA4 and POLE, and a mutational signature consistent with high tumor mutational burden (TMB), suggesting potential immunogenicity." (PMID 41768232, 2026). "POLEmut-MMRd/MSI tumors generally retained POLE-mutated features, including ultrahigh tumor mutational burden (TMB), early-stage disease, and favorable clinicopathological characteristics, consistent with a highly immunogenic phenotype." (PMID 41899533, 2026). "One hypermutated ChRCC tumor with the POLE and POLD1 mutations displayed SBS26 and SBS44, reflective of dMMR." (PMID 41563788, 2026). "POLE-mutated tumor analysis demonstrated a miRNA signature, with 19 miRNAs significantly down-regulated, including let-7f-5p and hsa-miR-200b-3p." (PMID 41226475, 2025). "Targeting the neoantigens generated by POLE mutations to obtain tumor-specific T cells is expected to be used in immunotherapy for various malignancies." (PMID 39931062, 2025). "We received a case from a 37-year-old Caucasian male diagnosed with treatment-naïve, moderately differentiated MSS CRC harboring POLE mutations, who underwent surgery for tumor removal." (PMID 40873566, 2025). "In vitro and in vivo models show that POLE mutations suppress tumor growth, reduce stemness, and increase T-cell infiltration, promoting an intrinsic immune response against tumor progression." (PMID 39949780, 2025). "Among the 8736 POLE variants, 2204 were reported both in the germline and as somatic mutations in tumours, 5872 only as germline variants, and 660 only as somatic variants." (PMID 41263451, 2025). "The experimental results fully demonstrated that the POLE mutation at this locus produced a new antigenic peptide, and the T cells generated against this antigen were found to have specific tumor-killing effects." (PMID 39931062, 2025). "When proofreading deficiency co-exists with MMR deficiency, the tumour mutational spectra shift to SBS14 in the case of POLE mutations and SBS20 for POLD1." (PMID 40237887, 2025). "Given the tumor’s POLE mutation, high TMB, and refractory response to cytotoxic therapy, the patient was considered for immunotherapy." (PMID 40710181, 2025). "Similar to MSI-H tumors, tumors with POLE/POLD1 mutations generally exhibit high tumor mutation burden (TMB)." (PMID 40308511, 2025). "The number of patients with varying degrees of tumor lymphocyte infiltration at the relevant POLE gene mutation locus was also analyzed." (PMID 39931062, 2025). "Mutations in POLE, as was also present in this tumor, are associated with a very high TMB, which was indeed observed in this patient (375.994 mutations/Mb)." (PMID 39876058, 2025). "While the POLE mutation is associated with an increased tumor burden and various other genetic deficiencies, the increased tumor immunogenicity enhances responsiveness to immune checkpoint inhibitors and offers a positive predictive biomarker for IO use." (PMID 40710181, 2025).
tumor (continued). "Mutations in the POLE gene result in the disruption of Pol ε repair function, leading to a significant increase in the number of mutations in tumor cells." (PMID 41009360, 2025). "While cancer overall is characterized by broad oncomiR up-regulation and loss of tumor-suppressive miRNAs, POLE-mutant tumors display a distinct profile marked by global down-regulation, reflecting alternative evolutionary strategies of tumor progression." (PMID 41226475, 2025). "Reflecting these insights, ESMO and NCCN guidelines now recommend testing for POLE/POLD1 mutations in MSS CRC with high tumor mutational burden particularly in right-sided tumors." (PMID 40805233, 2025). "Retrospective molecular analysis of this tumor revealed a pathologic POLE-EDM (p.V411L) as well as a loss in MMR protein PMS2 and according to the FIGO 2023 classification would now be categorized as stage IAmPOLEmut." (PMID 40958870, 2025). "Hypermutated tumours are commonly related to mutations in genes encoding mismatch/proofreading activity, such as DNA polymerase epsilon (POLE), and can lead to microsatellite instability." (PMID 40702107, 2025). "The LGR5+ stem‐like cell signature exhibited significant associations with MSI status, POLE mutations, and tumor staging." (PMID 40661135, 2025). "The signatures SBS10a and SBS10b, associated with MSS POLE mutated tumours, co-occurred with SBS2829 (r = 0.48 and 0.61, FDR-adjusted P = 5.13 × 10−62 and 5.04 × 10−107) and the new DBS-CRC5 signature (r = 0.43, FDR-adjusted P = 8.21 × 10−47)." (PMID 39112715, 2024). "Given the critical role of infiltrating and activated cytotoxic T cells in antitumor immunity, we next sought to investigate the impact of POLE mutation on tumor growth and T cell infiltration." (PMID 38238314, 2024). "The discovery of MSI and POLE exonuclease domain mutations provides further insight into tumor behavior and potential therapeutic targets." (PMID 38893238, 2024). "The impact of POLE mutations on immunotherapy extends to their interaction with the tumor microenvironment." (PMID 39839672, 2024). "In EC, the ultramutated phenotype caused by POLE-EDM mutations has been shown to cause a “self-limiting” tumor progression with excellent prognosis after surgery." (PMID 39239272, 2024). "In total, 15 HM tumours were MSS with POLE or other DNA-damage-repair gene mutations and 6 were MSS with high non-coding tumour mutation burden (TMB) but no repair gene mutations." (PMID 39112715, 2024). "The exome analysis of the initial tumor revealed mutation in two genes, RET and POLE, which were also present in all the cells of the initial and in the tumor recurrence." (PMID 39273494, 2024). "One indirect approach to identify POLE-mutated cancers is by looking at the number of tumor-infiltrating lymphocytes (TILs), as we know that a highly mutated microenvironment expresses more antigens and, therefore, activates the host’s immune system." (PMID 39239272, 2024). "In these ultra-hypermuted tumor cases, a secondary somatic event such as an inactivating mutation in POLE or POLD1 genes is considered to be responsible for the mutation burst(s) leading to the ultra-hypermutated phenotype." (PMID 39233831, 2024). "Beyond the high mutational burden caused by these mutations, this intrinsic attenuation of DNA damage repair in tumor cells with POLE mutation exacerbates genomic replication stress and chromosomal instability." (PMID 38238314, 2024). "What is the role of immunotherapy in POLE-mutated tumors and do POLE variants impact other tumor entities comparably?" (PMID 39239272, 2024). "Park and colleagues employed the 3-nucleotide context approach to demonstrate that, in the presence of a POLE ExoD driver, tumor mutations predominantly emerge within certain nucleotide trios." (PMID 38282550, 2024).